ACE (angiotensin I converting enzyme)
Diseases named in the same sentence as ACE in open-access papers (continued):
Sharing a sentence is not in itself a finding about the gene and the disease.
viral pneumonia (3 papers, 2021 to 2023). Inflammation of the lung parenchyma that is caused by a viral infection. "The serum ACE levels and ACE gene polymorphisms were successfully evaluated with respect to subsequent viral pneumonia using records of 100 patients with viral pneumonia and 100 healthy controls." (PMID 36505135, 2022). "This study seeks to investigate the distribution of the angiotensin-converting enzyme (ACE) gene polymorphism and serum levels in patients with viral pneumonia and predict which polymorphism will lead to severe progression of the disease." (PMID 36505135, 2022). "Therefore, due to the ACE/ACE2 imbalance occurring in atypical viral pneumonia, we do find definitely increased Ang II and dramatically decreased Ang1-7 levels mostly in tissues but also in extracellular fluids." (PMID 37476705, 2023). "In addition, a recent study by Christopher Henry also observed lower rates of death and intubation with continued use of ACE inhibitors than with terminated use (OR = 0.25; 95% CI, 0.09–0.64) throughout the hospital stay in cases of viral pneumonia not due to coronavirus." (PMID 34490373, 2021).
Zinc deficiency (3 papers, 2018 to 2022). A deficiency of the essential metal Zinc; an essential cofactor for many enzymes. "Also, in HF patients, treatment with angiotensin-converting enzyme (ACE) inhibitors and angiotensin receptor blockers (ARBs) results in increased urinary zinc excretion and zinc deficiency." (PMID 29682528, 2018).
adenoma (2 papers, 2018 to 2022). A neoplasm arising from the epithelium. "Alternatively, it may be possible that an effect of ACE inhibition on cancer is restricted solely to the earliest stages of the adenoma-carcinoma sequence and therefore may not influence cancer risk among largely middle-aged participants of clinical trials if dysplasia is already present." (PMID 35113855, 2022).
adult respiratory distress syndrome (2 papers, 2005 to 2021). "Therefore, in this study, we investigated the association of the ACE insertion/deletion (I/D) polymorphism of the 287 bp Alu repeat to the susceptibility to SARS and the development of adult respiratory distress syndrome (ARDS) with a larger population." (PMID 15819995, 2005).
Alkalosis (2 papers, 2024 to 2025). Depletion of acid or accumulation base in the body fluids. "This suggests a potential association of the ACE II genotype with the development of respiratory alkalosis during intense exertion." (PMID 39599731, 2024).
alopecia (2 papers, 2023 to 2024). Hair loss usually from the scalp. "Research has found that serum ACE levels are higher in more severe cases of AA, while ACE levels in alopecia tissue are significantly lower than in controls." (PMID 39021569, 2024).
aneurysmal disease (2 papers, 2013 to 2014). "There is a remarkable inconsistency with respect to a role of ACE inhibitors in aneurysmal disease." (PMID 25474105, 2014). "The genetic loss of ACE2 in mice causes increased levels of Angiotensin-II and progressive mild LV dilatation with concomitant systolic dysfunction that is restored by ACE deletion, suggesting that this response is mediated by an increase in Angiotensin-II levels." (PMID 23630610, 2013).
asbestosis (2 papers, 2012 to 2013). A lung disorder caused by inhalation of asbestos fibers. "NSIP-like histology was seen in asbestosis and bone marrow transplantation, UIP-like changes in Jo-1 syndrome and after ACE inhibitor therapy." (PMID 23181688, 2012).
atrophic gastritis (2 papers, 2011 to 2021). "ACE I/D polymorphism was not linked with gastric atrophy in Asian subjects." (PMID 21864388, 2011).
Barrett esophagus (2 papers, 2019 to 2021). Esophageal lesion lined with columnar metaplastic epithelium which is flat or villiform. "On the one hand, RAS factors, such as angiotensin-converting enzyme (ACE) and the angiotensin II subtype 1 receptor (AT1R), seem to be upregulated in Barrett’s esophagus but, on the other hand, no prognostic effects of RAS-inhibition have been found in both ESCC and EAC so far." (PMID 34572905, 2021).
Becker muscular dystrophy (2 papers, 2023 to 2024). Becker muscular dystrophy (BMD) is a neuromuscular disease characterized by progressive muscle wasting and weakness due to degeneration of skeletal, smooth and cardiac muscle. "All the patients with Duchenne and Becker muscular dystrophy (BMD) were treated with Angiotensin-converting enzyme (ACE) inhibitors prior to any onset of cardiac symptoms, and one patient with calpainopathy was treated with ACE after the onset of cardiac signs." (PMID 37371191, 2023).
Behcet disease (2 papers, 2016 to 2023). A chronic, relapsing, multisystemic vasculitis characterized by mucocutaneous lesions, as well as articular, vascular, ocular and central nervous system manifestations. "The ACE gene polymorphism also contributes to an increased predisposition to Behcet disease (BD)." (PMID 37998534, 2023).
brain injury (2 papers, 2023 to 2025). Acute and chronic (see also brain INJURIES, CHRONIC) injuries to the brain, including the cerebral hemispheres, CEREBELLUM, and brain STEM. "ACE inhibitor-induced increase in SP has also been observed in rat brain after traumatic brain injury, indicating that ACE plays an important role in SP degradation." (PMID 37237567, 2023).
calcinosis (2 papers, 2020 to 2024). Deposition of calcium in the tissues. "Utilizing calcinosis-reducing drugs (such as bisphosphonate, denosumab, ectonucleotidase, and ACE inhibitors) for AS therapy focusing on the calcinosis step has been proposed." (PMID 32664529, 2020).
childhood cancer (2 papers, 2016 to 2024). "Previous studies have shown that while ACE-inhibition may attenuate cardiac remodeling in anthracycline-exposed Stage B childhood cancer survivors, this improvement is short-lived." (PMID 27716152, 2016).
Cholestatic liver disease (2 papers, 2025). "Blood tests revealed low platelet count, cholestatic liver disease, coagulopathy, high ferritin level, elevated angiotensin converting enzyme (ACE), and TRACP-5b levels." (PMID 40236727, 2025). "After initiating ERT, hepatosplenomegaly and the collodion skin improved; in addition, blood tests showed increased platelet counts, improved cholestatic liver disease, and decreased ACE levels." (PMID 40236727, 2025).
complex regional pain syndrome (2 papers, 2022 to 2025). A chronic pain syndrome characterized by a disproportionate spontaneous or stimulus-induced pain, accompanied by a variably mixed myriad of autonomic and motor disorders including symptoms such as swelling, allodynia, skin blood supply and trophic disturbances. "Using this tool, we have shown that the ACE serum activity was compromised in patients with complex regional pain syndrome (CRPS), a disease where symptoms develop locally." (PMID 35330406, 2022).
congenital malformations (2 papers, 2023 to 2024). "ACE inhibitors in the first trimester of pregnancy were proven to be teratogenic and increased the risk of congenital malformations, while in mothers exposed to ACE inhibitors in the second and third trimesters the well-characterized fetopathy was deemed to potentially develop." (PMID 37507894, 2023). "There is strong evidence that ACE inhibitors and calcium channel blockers (CCBs) are beneficial for kidney and immune function, and CCBs showed a safe profile for disorders of pregnancy." (PMID 39567981, 2024).
Cushing syndrome (2 papers, 2025). Cushing's syndrome (CS) encompasses a group of hormonal disorders caused by prolonged and high exposure levels to glucocorticoids that can be of either endogenous (adrenal cortex production) or exogenous (iatrogenic) origin. "In conclusion, patients with ACTH-dependent Cushing’s syndrome have concentrations of angiotensin I and angiotensin II within their typical ranges, but a moderately reduced ACE activity." (PMID 39804209, 2025). "This reflects a significantly reduced ACE activity in Cushing’s syndrome patients compared to controls." (PMID 39804209, 2025). "We found a specific RAS profile in patients with ACTH-dependent Cushing’s syndrome with concentrations of angiotensins I and II comparable to controls, but a moderately reduced ACE activity." (PMID 39804209, 2025). "While the design of our study does not allow to draw conclusions regarding the optimal antihypertensive treatment for patients with Cushing’s syndrome, the reduction in ACE activity does not support the use of an ACE inhibitor as first-line treatment as suggested by some authors." (PMID 39804209, 2025).
cystic kidneys (2 papers, 2021 to 2024). "This hypothesis is supported by high renin levels, angiotensin-converting enzyme (ACE), angiotensinogen, and angiotensin II in the fluid within renal cysts." (PMID 39200287, 2024).
cystinosis (2 papers, 2016 to 2025). Cystinosis is a metabolic disease characterized by an accumulation of cystine inside the lysosomes, causing damage in different organs and tissues, particularly in the kidneys and eyes. "For KQ11, there is very low CoE for effectiveness and safety of RAAS blockade (angiotensin converting enzyme [ACE]-inhibitor/angiotensin receptor blockers [ARB]) compared to no intervention in participants with cystinosis." (PMID 40877952, 2025).
dysautonomia (2 papers, 2022 to 2025). An acute or chronic disorder, affecting the sympathetic or parasympathetic nervous system. "The symptomatic treatment of dysautonomia consisted of beta blockers, calcium channel blockers, and ACE inhibitors." (PMID 35860488, 2022).
endotoxemia (2 papers, 2018 to 2023). "Together, endotoxemia and Ang1-7 offset in sexually-related manners imbalances in renal vasoconstriction and AT1/ACE/ACE2 signaling in PE offspring." (PMID 36650223, 2023).
germinoma (2 papers, 2020 to 2022). A malignant germ cell tumor arising in the central nervous system. "Serum ACE levels were checked in 6 of our patients, 3 of whom had elevated concentrations (two patients were finally diagnosed with germinoma, and one was monitored for LGG)." (PMID 35669693, 2022).
gingival hyperplasia (2 papers, 2021 to 2022). "angiotensin-converting enzyme (ACE) inhibitors, such as captopril and enalapril, and calcium channel blockers, such as nifedipine, are known to cause gingival hyperplasia, while the use of oral anticoagulants may lead to bleeding gums." (PMID 35845078, 2022).
gingivitis (2 papers, 2015 to 2025). A disorder involving inflammation of the gums; may affect surrounding and supporting structures of the teeth. "Increased levels of ACE in the case group indicated the precancerous nature of desquamative gingivitis associated with OLR." (PMID 40265032, 2025). "Fluorometric analysis indicated increased ACE activity in gingiva samples from volunteers with gingivitis compared to the healthy group (p-value = 0.02)." (PMID 26244896, 2015). "ACE activity was significantly increased in samples obtained from humans with gingivitis compared to healthy individuals." (PMID 26244896, 2015). "When compared to healthy tissue, ACE activity was increased in human gingiva from volunteers with gingivitis." (PMID 26244896, 2015).
HCMV infection (2 papers, 2018 to 2020). "Moreover, HCMV infection results in decreased ACE and increased HSD3B2 methylation." (PMID 29752343, 2018).
high output heart failure (2 papers, 2021 to 2024). High-output heart failure is a heart condition that occurs when the cardiac output is higher than normal. "Our present study was directly aimed to compare important differences in renal hemodynamics between long-term treatment with an ACE inhibitor or AT1 receptor blocker during high-output heart failure." (PMID 33608612, 2021). "In conclusion, dissimilar to an ACE inhibitor administration, an AT1 receptor blocker treatment was shown to prevent renal hypoperfusion and hypoxia in rats with high-output heart failure." (PMID 33608612, 2021).
hydronephrosis (2 papers, 2012 to 2020). Collection of urine in the renal pelvis that results in dilatation of the renal pelvis and calyces. "Mutations in the genes encoding for angiotensinogen (AGT), renin, ACE, or angiotensin II receptor type 1 (AGTR1) in mice result in severe medullary hypoplasia and hydronephrosis, a phenotype not observed in humans with AGT, renin, ACE, or AGTR1 mutations." (PMID 22685656, 2012).
hyperaldosteronism (2 papers, 2021 to 2024). Overproduction of aldosterone by the adrenal glands, which may lead to hypokalemia and/or hypernatremia. "Subjects with hyperaldosteronism, as well as subjects on chronic treatment with angiotensin-converting enzyme (ACE) blockers or angiotensin type 1 receptor antagonists, exhibit increased Aldo levels, an event known as “aldosterone breakthrough”." (PMID 34200377, 2021). "Among the parameters with only a minor influence (e.g., aldosterone normal concentration or rate constant for interstitial and intracellular potassium exchange), we kept the hyperaldosteronism effect as it could also indirectly represent a possible suppressive effect of ACE inhibitors (as a proxy)." (PMID 39204148, 2024).
Hypocalcemia (2 papers, 2024). An abnormally decreased calcium concentration in the blood. "Relative contraindications include recent use of angiotensin-converting enzyme (ACE) inhibitors and hypocalcemia." (PMID 39092386, 2024).
intracranial hemorrhage (2 papers, 2021 to 2026). Bleeding within the SKULL, including hemorrhages in the brain and the three membranes of MENINGES. "According to a recent meta-analysis, it has been demonstrated that ACE I/D polymorphism is associated with intracranial hemorrhage." (PMID 34451921, 2021). "A recent meta-analysis including 39 case–control studies showed that ACE I/D polymorphism was significantly associated with intracranial hemorrhage, especially among Asians." (PMID 34451921, 2021). "Adverse reactions to angiotensin-converting enzyme (ACE) inhibitors have been demonstrably more prevalent in African Americans compared to white Americans, and the risk of hemorrhagic complications in patients with intracranial hemorrhage treated with thrombolytics shows a similar relationship." (PMID 41608647, 2026).
Kawasaki disease (2 papers, 2017 to 2020). A rare inflammatory disease characterized by an acute febrile, systemic, self-limiting, medium-vessel vasculitis primarily affecting children. "The angiotensin-converting enzyme (ACE) I/D polymorphism has been reported tobe associated with Kawasaki disease (KD), but studies to date presentconflicting results." (PMID 29937869, 2017).
lichen planus (2 papers, 2018 to 2020). A chronic, recurrent, pruritic inflammatory disorder of unknown etiology that affects the skin and mucus membranes. "Lichen planus (LP) is a chronic inflammatory disease that affects the skin, hair, nails, and mucous membranes, with variants such as drug-induced lichen planus, which is triggered by medications such as angiotensin-converting enzyme (ACE) inhibitors and antimalarials." (PMID 33269137, 2020).
liver dysfunction (2 papers, 2024 to 2025). "Warnings about liver dysfunction in Japanese package inserts vary among angiotensin-converting enzyme (ACE) inhibitors, and risk assessment of liver dysfunction with ACE inhibitors has been limited." (PMID 41073682, 2025). "Although ethnic factors on drug responses should be taken into consideration, the finding of increased risk of liver dysfunction with ACE inhibitors in Japanese patients provide valuable insights into their safety profile and appropriate clinical use." (PMID 41073682, 2025). "The risk of liver dysfunction observed in this study was inconsistent among ACE inhibitors in comparison with enalapril maleate in both primary and secondary outcomes." (PMID 41073682, 2025). "To evaluate the risk of liver dysfunction among patients prescribed ACE inhibitors available in Japan, we conducted this study based on the real-world data from MID-NET®." (PMID 41073682, 2025). "It should be noted that the 95% CIs including 1.0 observed for many ACE inhibitors compared to enalapril maleate may imply the risk of liver dysfunction because the PI of enalapril maleate includes the liver dysfunction warning as CSAR." (PMID 41073682, 2025). "In the United States, the package inserts (PIs) of all ACE inhibitors include warnings related to liver dysfunction under the “WARNINGS AND PRECAUTIONS” section." (PMID 41073682, 2025). "The incidence proportions of liver dysfunction for each ACE inhibitor in this study were approximately 1–5%, which are relatively higher than those reported in previous studies (0.2–2%)." (PMID 41073682, 2025). "We identified patients who were newly prescribed ACE inhibitors between January 1, 2009 and December 31, 2019 and excluded patients with liver dysfunction before the first prescription of ACE inhibitors." (PMID 41073682, 2025). "No clear increase in the risk of liver dysfunction was observed with ACE inhibitors that do not carry a liver dysfunction-related warning in Japan." (PMID 41073682, 2025). "These suggests that the risk of liver dysfunction with ACE inhibitors is unlikely to be a class-effect." (PMID 41073682, 2025). "This study suggests that the risk of liver dysfunction with ACE inhibitors is unlikely to be a class-effect." (PMID 41073682, 2025). "However, liver dysfunction is known as one of the adverse reactions to ACE inhibitors." (PMID 41073682, 2025). "The risk of liver dysfunction with ACE inhibitors is unlikely to be a class-effect." (PMID 41073682, 2025). "In taking all results into consideration, it suggests that no additional safety measures are necessary at present for ACE inhibitors that do not carry a liver dysfunction-related warning as CSAR in Japan." (PMID 41073682, 2025). "Although continuous safety monitoring is necessary for promoting proper use of ACE inhibitors, the results indicate that no additional safety measures are currently required for ACE inhibitors that do not carry a liver dysfunction-related warning in Japan." (PMID 41073682, 2025). "Our findings suggested that ARB/ACE inhibitor use may upregulate ACE2 receptor expression in biliary and hepatic epithelial cells, which could lead to liver dysfunction in ARB/ACE inhibitor users." (PMID 39194933, 2024).
melancholic depression (2 papers, 2016 to 2020). "Studies suggest that the angiotensin-converting enzyme (ACE) could be decreased in melancholic depression (vs. atypical, vs. healthy controls), although published results are inconsistent." (PMID 33255237, 2020). "The study demonstrated that in atypical depression the following molecules were altered as compared to melancholic depression: higher leptin, FABPa, complement C3, insulin, B2-microglobulin, ACE, and lower insulin-like growth factor-binding protein 1 and 2 (IGFBP1, IGFBP2) and mesothelin." (PMID 33255237, 2020). "One other marker of interest is the ACE, which may be a marker that is specific to melancholic depression." (PMID 27404283, 2016). "No mediation was found for IGFBP1, ACE and B2M (comparison atypical and melancholic depression) and B2M, ANG2 and VWF (comparison atypical depression and controls)." (PMID 27404283, 2016).
membranous nephropathy (2 papers, 2013 to 2023). "In the clinical practice, angiotensin converting enzyme (ACE) inhibition or angiotensin receptor blockade is still most common strategy against membranous nephropathy or, rather, more aggressive treatment using glucocorticoids and alkylating agents." (PMID 23990847, 2013).
metastatic melanoma (2 papers, 2020 to 2025). A melanoma that has spread from its primary site to another anatomic site. "This is relevant, as metastatic melanoma express components of the renin–angiotensin system: PRR, AT2R, and ACE, with ACE localizing to the endothelium of tumor microvessels." (PMID 39941158, 2025).